MIR20B (microRNA 20b)
Synonyms: hsa-mir-20b; MIRN20B; mir-20b
Gene: MicroRNA gene on chromosome X (134,169,809 to 134,169,877, reverse strand). Ensembl gene ENSG00000284043.
Gene Ontology:
Biological process: miRNA-mediated post-transcriptional gene silencing
Cellular component: RISC complex
Homologues: Orthologues: chimpanzee ptr-mir-20b (100% identical), macaque mml-mir-20b (99% identical), guinea pig MIR20B (97% identical), pig ssc-mir-20b-1 (93% identical), dog MIR20B (84% identical), tropical clawed frog xtr-mir-20b (83% identical). Paralogues in human: MIR20A (78% identical), MIR17 (68% identical), MIR106B (61% identical), MIR18A (54% identical).
Diseases named in the same sentence as MIR20B in open-access papers:
MIR20B is named in the same sentence as 13 diseases in open-access papers, as found by Europe PMC text mining. Sharing a sentence is not in itself a finding about the gene and the disease. The quoted sentences say what the papers report.
esophageal cancer (1 paper, 2016). A primary or metastatic malignant neoplasm involving the esophagus. "Follow-up experiments indicated transfection of MIR20b, MIR30e, MIR498 and MIR196 affected the apoptotic pathway in esophageal cancers cells." (PMID 27462775, 2016). "Collectively, above results suggested that the four predicted miRNAs, MIR20b, MIR30e, MIR498 and MIR196 may be involved in the apoptotic pathway in esophageal cancers cells." (PMID 27462775, 2016).
Hepatic steatosis (1 paper, 2021). Steatosis is a term used to denote lipid accumulation within hepatocytes. "We next observed that AAV-anti-Mir20b administration reduced liver weight and hepatic steatosis in HFD-fed mice than in AAV-Control mice." (PMID 34964438, 2021). "Taken together, these results indicate that Mir20b plays an important role in the development of fibrosis, inflammation, and hepatic steatosis in NAFLD progression." (PMID 34964438, 2021). "AAV-anti-Mir20b or fenofibrate administration significantly reduced the liver weight and hepatic TG levels, and co-administration further reduced hepatic steatosis." (PMID 34964438, 2021). "We next observed that AAV-anti-Mir20b administration significantly reduced hepatic steatosis in MCD-fed mice than in AAV-Control mice." (PMID 34964438, 2021). "Inhibition of Mir20b alleviates hepatic steatosis in HFD-fed mice." (PMID 34964438, 2021).
hepatocellular carcinoma (1 paper, 2021). A malignant tumor that arises from hepatocytes. "Interestingly, it has been reported that upregulated Mir20b highly regulates cancer cell proliferation and promotes proliferation of H22 hepatocellular carcinoma cells." (PMID 34964438, 2021).
Hyperoxaluria (1 paper, 2025). Increased excretion of oxalates in the urine. "Furthermore, reduced MIR20B-3p expression levels have been observed in the urine of patients with hyperoxaluria and in rat models of ethylene glycol-induced hyperoxaluria." (PMID 40851276, 2025).
liver cancer (1 paper, 2021). An epithelial or non-epithelial malignant neoplasm that arises from the liver. "Thus, plasma MIR20B can be a promising target in liver cancer development." (PMID 34964438, 2021).
liver fibrosis (1 paper, 2021). "This implies that MIR20B is able to set up an NR transcription program similar to that of NASH and liver fibrosis." (PMID 34964438, 2021). "Thus, our study strongly suggested that MIR20B regulates the pathogenesis of NAFLD, but might also be relevant in the development of severe stages of liver fibrosis and even in HCC." (PMID 34964438, 2021).
Obesity (1 paper, 2021). Accumulation of substantial excess body fat. "To confirm the in vivo roles of Mir20b in obesity model mice, we introduced Mir20b using an adenovirus-associated vector (AAV), referred to as AAV-Mir20b, into C57BL/6 mice that had been fed a normal chow diet (NCD) or a high-fat diet (HFD)." (PMID 34964438, 2021). "The expression of MIR20B was upregulated in free fatty acid (FA)-treated hepatocytes and the livers of both obesity-induced mice and NAFLD patients." (PMID 34964438, 2021). "A previous study demonstrated that upregulated MIR20B levels in obesity-induced metabolic disorders such as T2DM were considered to prevent several targets, such as STAT3, CD36, and PTEN, which are involved in glucose and lipid homeostasis." (PMID 34964438, 2021). "Together, these results suggest that suppression of Mir20b could ameliorate NAFLD by recovering lipid metabolism in a HFD-induced obesity model." (PMID 34964438, 2021).
steatosis (1 paper, 2021). Increased lipid within the cytoplasm of cells. "MIR20B showed the deteriorating effects on FA oxidation, steatosis, inflammation, and fibrosis in HFD- or MCD-fed mice." (PMID 34964438, 2021). "Liver sections clearly showed a decrease in both steatosis and fibrosis with AAV-anti-Mir20b administration in MCD-fed mice." (PMID 34964438, 2021). "While the expression of other candidates, including RORA, RORC, and THRB, remained unchanged, that of PPARA significantly decreased as NAFLD progressed to steatosis and NASH, and showed a negative correlation with that of MIR20B." (PMID 34964438, 2021).
type 2 diabetes mellitus (1 paper, 2021). A type of diabetes mellitus that is characterized by insulin resistance or desensitization and increased blood glucose levels. "Previous report has demonstrated that MIR20B, a member of the MIR17 family, presents in the circulating plasma of NAFLD patients and has been highlighted as a novel biomarker of NAFLD and type 2 diabetes mellitus (T2DM) for the diagnosis and risk estimation of NAFLD." (PMID 34964438, 2021).
MIR20B also shares sentences with these, for which no sentence is quoted: Alzheimer disease (1 paper); cancer (1); metabolic disorders (1); nonalcoholic fatty liver disease (1).